EPAS1 (endothelial PAS domain protein 1)
Diseases named in the same sentence as EPAS1 in open-access papers (continued):
Sharing a sentence is not in itself a finding about the gene and the disease.
gastric cancer (24 papers, 2008 to 2025). A primary or metastatic malignant neoplasm involving the stomach. "For instance, PXR activation by anisomycin was associated with an increase in the interaction PXR–EPAS1 (endothelial PAS domain protein 1) in BGC823 gastric cancer cells." (PMID 34831358, 2021). "Representative genes include VWF and EPAS1 that allow for prognosis differentiation in various gastric cancer treatment cohorts as well as response and survival discrimination in immunotherapy." (PMID 39901877, 2025). "It has been reported that the abnormal expression of EPAS1 is closely related to the resistance of non-small cell lung cancer to tyrosine kinase inhibitors (TKIs) as well as to multidrug resistance in gastric cancer 17-18." (PMID 32913475, 2020). "Particularly, high expression of EPAS1 is closely related to cisplatin resistance in lung adenocarcinoma and multidrug resistance in stomach cancer 38,18." (PMID 32913475, 2020).
ovarian carcinoma (24 papers, 2012 to 2026). A malignant neoplasm originating from the surface ovarian epithelium. "Both the high transduction efficiency and the increased mRNA and protein expression of HIF‐1α and HIF‐2α in HIF‐1A‐cDNA‐transduced and EPAS1‐cDNA‐transduced cells indicate that ovarian cancer cells successfully overexpressed either HIF‐1α or HIF‐2α." (PMID 30536571, 2019). "Additionally, the activation of HIF1A and EPAS1 in cancer is connected with the vascularization processes, and ovarian carcinoma cells have been shown to express elevated VEGFA levels." (PMID 36230822, 2022). "In vitro findings suggest that nuclear HIF1A has prognostic importance in ovarian cancer, and EPAS1 may play a crucial role in the carcinogenesis and progression of ovarian malignancies." (PMID 36230822, 2022). "In other gynecological malignancies—ovarian cancer, we also observed differences in HIF1A and VEGFA expression levels in a case–control study, but also EPAS1 differed significantly." (PMID 39888575, 2026). "Nevertheless, data regarding HIF1A, EPAS1, and VEGFA expression in ovarian cancer are scant." (PMID 36230822, 2022). "On the other hand, in ovarian cancer tissue samples, VEGFA was correlated neither with HIF1A nor EPAS1, but HIF1A was positively and moderately correlated with EPAS1 (R = 0.57, p < 0.0001)." (PMID 36230822, 2022).
non-small cell lung carcinoma (23 papers, 2007 to 2025). A group of at least three distinct histological types of lung cancer, including non-small cell squamous cell carcinoma, adenocarcinoma, and large cell carcinoma. "In non-small cell lung cancer, EPAS1 bound directly to EGFR with a TKI-resistant T790M mutation; however, it did not bind to the wild-type EGFR." (PMID 36313570, 2022). "The A allele at rs13419896 of EPAS1 is associated with an enhanced expression and prognosis for non-small cell lung cancer." (PMID 35071338, 2021). "Studies have demonstrated that EPAS1 is regulated by DNA methyltransferases (DNMTs) in non-small cell lung cancer (NSCLC)." (PMID 38612943, 2024). "A mechanism of negative feedback regulation for the EPAS1 gene was also suggested in non-small cell lung cancer cells, where HIF2α mRNA was regulated by DNA methyltransferases (DNMTs)." (PMID 34209205, 2021). "EPAS1 may function as a link between stimulation of MET and T790M EGFR, indicating that this protein may be a potential treatment target, particularly in non-small cell lung cancers resistant to TKIs." (PMID 36313570, 2022).
Hypertension (21 papers, 2015 to 2026). The presence of chronic increased pressure in the systemic arterial system. "Endothelial-specific deletion of EPAS1 induced the loss of GEnC fenestrations and enhanced endothelial swelling in experimental hypertension-induced secondary FSGS." (PMID 33123011, 2020). "In the case of EPAS1 gene expression, it was found to be more than two-fold higher in the material collected from patients with hypertension during pregnancy (p = 0.031)." (PMID 39456823, 2024). "However, we identified novel genes (SBF2, ARHGAP12, EPAS1, CLEC16A, and LRPPRC) to be associated with hypertension." (PMID 41898884, 2026). "Thus, it is understandable why EPAS1 gene expression is higher in women suffering from a chronic disease such as hypertension." (PMID 39456823, 2024). "In addition, our results showed that speckled teal had additional outliers in EPAS1 located in exon 6, which has been identified in human high-altitude populations to be responsible for adaptive changes in heart rate and hypertension." (PMID 30631144, 2019). "Moreover, the occurrence of increased EPAS1 expression may influence the pathogenesis of hypertension." (PMID 39456823, 2024). "Moreover, the higher expression of EPAS1 in cells from the milk of mothers with hypertension during pregnancy and those who did not supplement iron during pregnancy was shown." (PMID 39456823, 2024). "Moreover, in the presence of hypertension and EPAS1, no podocyte lesions were observed, indicating that endothelial-specific EPAS1 gene deletion exacerbates proteinuria and results in severe podocyte damage." (PMID 38374141, 2024).
metastatic tumors (17 papers, 2013 to 2024). "Three tumors were from patients who developed metastatic disease (E205, PC, EPAS1; E206, PC, EPAS1; E235, PC, MAML3-fusion), and two tumors had locally invasive features (E007, TMEM127; E025, AT-PG, SDHA)." (PMID 36271074, 2022). "The sensitivities to the different imaging modalities depend on the presence of PGL versus PCC, HN PGLs, sporadic metastatic, or non-metastatic disease, cluster 1 Krebs cycle-related SDHx mutations and VHL/EPAS1 pseudohypoxia-related mutations or cluster 2 kinase signaling-associated mutations." (PMID 31597347, 2019). "We also found higher frequencies of homozygous deletions for EPCAM and EPAS1 in MMR-d primary tumors and for EPCAM in MMR-d metastatic tumors." (PMID 36675550, 2023). "However, many patients with the metastatic tumours had shown lower EPAS1 mRNA expression when compared to that of non-metastatic patients (p = 0.057)." (PMID 33114456, 2020). "We next tested the hypothesis that EPAS1 activity is significantly different in SDHB-null metastatic tumors vs. those annotated as “non-malignant”." (PMID 31234811, 2019).
lung adenocarcinoma (15 papers, 2013 to 2024). A carcinoma that arises from the lung and is characterized by the presence of malignant glandular epithelial cells. "As expected, several members of the HIF gene family were at the centre of the molecular network and more interestingly, EPAS1 (also known as HIF-2α) SNP rs12614710 was associated with lung adenocarcinoma." (PMID 34298636, 2021). "EPAS1 (endothelial PAS domain-containing protein 1) is downregulated in NSCLC due to promoter methylation and sequence genetic polymorphisms, and specifically in lung adenocarcinoma." (PMID 36101460, 2022). "The subsequent multivariate regression analysis revealed that T stage, N stage, and EPAS1 expression were independent prognostic factors for lung adenocarcinoma (p<0.05)." (PMID 34729113, 2021). "Cox univariate regression analysis revealed that clinical stage, T stage, N stage, and EPAS1 expression levels were the primary factors affecting lung adenocarcinoma recurrence and metastasis." (PMID 34729113, 2021). "As for Epas1, it was reported that Src kinases mediate the hypoxia-induced expression of EPAS1 mRNA in human lung adenocarcinoma cells." (PMID 23441228, 2013). "EPAS1 rs4953354 polymorphism is related to gene expression and NSCLC susceptibility, specifically in female never- smokers with lung adenocarcinoma, along with DNA methylation regulation of mRNA levels." (PMID 36661515, 2023).
diabetes (14 papers, 2018 to 2025). "Another study investigating differential monocyte gene expression in individuals with diabetes identified IRF1, GATA6, SP11, EPAS1, NFKB2, and STATB3 as key affected transcription factors." (PMID 40476695, 2025). "Key examples include IRF1, GATA6, SPI1, EPAS1, NFKB2, and STAT5B, which are involved in immune response, cell differentiation, and metabolic regulation, all of which are critical in diabetes pathogenesis." (PMID 39877357, 2024). "Unlike rs6756667 in EPAS1, relationships with the SNP rs3025039 and other VEGFA gene variants have been widely reported for HA illness and for cancer, heart disease, diabetes, neurological diseases and many other types of diseases." (PMID 32718338, 2020).
leukemia (14 papers, 2011 to 2024). A malignant (clonal) hematologic disorder, involving hematopoietic stem cells and characterized by the presence of primitive or atypical myeloid or lymphoid cells in the bone marrow and the blood. "This is basically consistent with the results of our EPAS1-related GSEA analysis, including biological processes such as leukemia-associated genetic alterations, epigenetic regulation, and immune microenvironment changes." (PMID 37124944, 2023). "Interestingly, LL-100 RNA-seq data of leukemia/lymphoma cell lines demonstrated elevated EPAS1 expression in ONECUT2-positive anaplastic large cell lymphoma (ALCL)-derived cell lines." (PMID 38474011, 2024).
von Hippel-Lindau syndrome (14 papers, 2016 to 2025). "The most well-known syndrome to associate erythrocytosis and tumorigenesis is von Hippel Lindau disease, but mutations in PHD1 and HIF2a (EPAS1) are also implicated in tumorigenesis." (PMID 27034858, 2016). "When HIF1A and EPAS1/HIF2A are hydroxylated, they are recognized by VHL, a tumour suppressor gene responsible for von Hippel–Lindau disease." (PMID 38276269, 2023).
lymph node metastasis (13 papers, 2013 to 2022). "EPAS1-altered tumors are associated with higher stage, grade, and lymph node metastasis as well as with shorter PFS (14 vs. 51 months, q = 0.01) and OS (15 vs. 55 months, q = 0.01)." (PMID 36421334, 2022). "The association of EPAS1 mutations with the presence of lymph node metastasis indicates that mutations in EPAS1 sequence could be predictive makers for lymph node metastasis." (PMID 33042797, 2020). "Similarly, high EPAS1 mRNA expression was associated with CRC without lymph node metastasis (p = 0.03)." (PMID 34250767, 2021). "Overall, 10% (n = 6/60) of ESCCs with metastatic carcinoma in the lymph node had EPAS1 mutations, whereas no mutation was detected in ESCC without lymph node metastasis." (PMID 33042797, 2020). "The results suggest that the expression of ECM2, PCDH12, EPAS1, CD93, DLL4, and ARHGEF15 are significantly different in age, N (lymph node metastasis status), and whether radiotherapy is received or not." (PMID 35953532, 2022).
liver fibrosis (12 papers, 2016 to 2025). "Finally, we show that GATA4 directly repressed EPAS1 transcription in hepatic stellate cells and that stabilization of the HIF2α protein in hepatic stellate cells leads to liver fibrosis." (PMID 34699385, 2021). "We also demonstrate that GATA4 regulated the expression of the endothelial PAS domain-containing protein 1 gene (EPAS1) and that EPAS1/HIF2α activity in HSCs induces liver fibrosis in mice." (PMID 34699385, 2021).
bladder cancer (11 papers, 2012 to 2024). "EPAS1 expressing TAMs were found to be associated with a poor prognosis of invasive bladder cancer, suggesting that EPAS1 expressed in a subset of TAMs mediates bladder cancer progression." (PMID 22811589, 2012). "In a clinical report on invasive bladder cancer, researchers found that the location of endothelial Per-ARNT-Sim (PAS) domain protein-1 (EPAS-1)/hypoxia-inducible factor-2α (HIF-2α) expression was identified mainly in TAMs, which is positively correlated with the expression of VEGF." (PMID 39606239, 2024).
myocardial infarction (11 papers, 2016 to 2025). Gross necrosis of the myocardium, as a result of interruption of the blood supply to the area, as in coronary thrombosis. "The increase of SLC2A3, EPAS1 and HMOX1 were risk factors for myocardial infarction, while ATM and FANCD2 were protective factors." (PMID 38253721, 2024). "SLC2A3, EPAS1, HMOX1, ATM and FANCD2 genes all had good diagnostic value for myocardial infarction (P < 0.05)." (PMID 38253721, 2024). "The increase of SLC2A3, EPAS1 and HMOX1 are risk factors for myocardial infarction, while ATM and FANCD2 are protective factors.Decision tree analysis showed that SLC2A3, HMOX1, ATM, FANCD2 gene had higher net yield in diagnosing myocardial infarction." (PMID 38253721, 2024). "ROC curves of 5 different genes related to ferroptosis associated with myocardial infarction showed that SLC2A3, EPAS1, HMOX1, ATM and FANCD2 genes had good diagnostic value for myocardial infarction, and the elevation of SLC2A3, EPAS1 and HMOX1 was a risk factor for myocardial infarction." (PMID 38253721, 2024). "ROC curves of 5 differentially ferroptosis-related genes associated with myocardial infarction showed that SLC2A3, EPAS1, HMOX1, ATM and FANCD2 genes had good diagnostic value for myocardial infarction, and the area under the curve had statistical significance (P < 0.05)." (PMID 38253721, 2024). "According to the method of systematic random sampling, the sample size was divided into test set and verification set, and the decision tree model of SLC2A3, EPAS1, HMOX1, ATM and FANCD2 genes on myocardial infarction was established." (PMID 38253721, 2024).
neuroendocrine tumors (11 papers, 2010 to 2025). "EPAS1 gene is active under hypoxic conditions and plays an essential role in the development of the heart and in the management of the catecholamine balance, mutations of which have been identified in neuroendocrine tumors." (PMID 31015364, 2019). "Thus, continued study of patients with PPGL affirms the emergence of EPAS1 mutations as a major driver of neuroendocrine tumor pathogenesis and solidifies the importance of systemic hypoxia or pseudohypoxia in PPGL tumorigenesis." (PMID 30135421, 2018).
preeclampsia (11 papers, 2013 to 2025). Preeclampsia is a hypertensive disorder of pregnancy that is characterized by new-onset hypertension with proteinuria presenting after 20 weeks of gestation, and depending on mild or severe forms may initially present with severe headache, visual disturbances, and hyperreflexia. "However, EPAS1 is considered a candidate gene as a potential biomarker of the susceptibility, early detection, and/or individualized maternal–infant care in case of preeclampsia." (PMID 28251419, 2017). "It was reported that the plasma concentration of HTRA1 increases in pregnancies complicated by preeclampsia and IUGR, whilst EPAS1 is typed as a biomarker of early preeclampsia detection." (PMID 31280246, 2019).
Sepsis (11 papers, 2016 to 2023). Sepsis is defined as life-threatening organ dysfunction caused by a dysregulated host response to infection. "Previous studies on the expression of EPAS1 in sepsis are contradictory as both up‐regulation and suppression have been found in sepsis patients." (PMID 35285058, 2022). "The authors identified regulatory genetic variants in this group that account for the upregulated expression of the genes HIF1A and EPAS1 (endothelial PAS domain protein 1), indicating that HIF genetic variants may be deterministic of host sepsis response." (PMID 37627293, 2023). "Therefore, we screened the ferroptosis-related genes (Hmox1, Epas1, Sirt1, Slc3a2, Jun, Plin2 and Zfp36) in this study through bioinformatics analysis, and found that these genes were highly expressed in sepsis-induced liver failure model." (PMID 35923893, 2022). "In general, the conclusions drawn from these reports are consistent with the results in our research, that is, Hmox1, Epas1, Sirt1, Slc3a2, Jun, Plin2 and Zfp36 collectively promote the development of sepsis-induced liver failure by interacting with B cells and NK cells." (PMID 35923893, 2022).
clear cell carcinoma (10 papers, 2021 to 2025). "EPAS1 promotes ferroptosis in clear cell carcinoma by upregulating hypoxia‐induced lipid droplet‐associated (HILPDA/HIG2)." (PMID 38722283, 2024). "EPAS1 promotes ferroptosis via hypoxia‐related genes in clear cell carcinomas." (PMID 38722283, 2024). "In some tumors, such as clear-cell carcinomas, EPAS1 may even promote the tumor-dependent ferroptotic death procession by recruiting some specific downstream factors." (PMID 34262953, 2021).
emphysema (10 papers, 2015 to 2025). "The EPAS1 target genes we predicted significantly overlap with genes associated with emphysema caused by smoking in mouse." (PMID 25569234, 2015). "Among the 104 emphysema severity associated genes in mouse, 30 of them overlap with the downstream genes regulated by EPAS1 (p-value = 5.1×10−15)." (PMID 25569234, 2015). "EPAS1 knockdown by siRNA in endothelial cells impacted genes that significantly overlapped with EPAS1 downstream genes in lung tissue including hypoxia responsive genes, and genes associated with emphysema severity." (PMID 25569234, 2015). "Expression levels of the remaining 26 genes are anti-correlated with EPAS1 methylation levels; their expression levels are expected to decrease as emphysema severity increases." (PMID 25569234, 2015). "Expression levels of 4 of the 30 overlapping genes are positively correlated with EPAS1 methylation levels indicating that their expression levels increase as emphysema severity increases." (PMID 25569234, 2015). "To investigate whether EPAS1 expression levels change when mice start to develop emphysema after chronic smoking exposure, we checked Epas1 expression levels in two different chronic smoking mouse models using C57BL/6J and A/J mice." (PMID 25569234, 2015).
steatosis (10 papers, 2016 to 2025). Increased lipid within the cytoplasm of cells. "Qu demonstrated that mice with liver-specific disruption of Vhl achieved EPAS1 overexpression and presented steatosis accompanied by pro-inflammatory and fibrogenic cytokine overexpression." (PMID 36923253, 2023).
breast tumor (9 papers, 2011 to 2024). "Candidates that exhibited the strongest association with breast tumors were regions from the longest introns of RFX2, EPAS1, RBMS1, ZEB2, and the three different introns of CRIM1." (PMID 25798919, 2015). "The positive correlation between both HIF-1α and EPAS1 (HIF-2α) mRNA levels and overall breast tumor hypoxia response suggests a role for transcriptional regulation of these hypoxia regulators." (PMID 21672245, 2011).
chondrosarcoma (9 papers, 2010 to 2023). A malignant cartilaginous matrix-producing mesenchymal neoplasm arising from the bone and soft tissue. "Chondrosarcoma patients carrying an amplified EPAS1 gene also tended to exhibit reduced disease-free survival compared to those without EPAS1 amplification (P = 0.0559)." (PMID 33024108, 2020). "A cross-check with the public dataset showed that the EPAS1 mRNA level was consistently elevated in spheres of primary cultured chondrosarcoma cells compared to their monolayer counterparts." (PMID 33024108, 2020). "HIF-2α is upregulated in high-grade chondrosarcoma biopsies and EPAS1 gene amplification is associated with poor prognosis in chondrosarcoma patients." (PMID 33024108, 2020). "We then examined the relationship between the presence of HIF1A or EPAS1 gene amplification and the occurrence of dedifferentiation, recurrence, or metastasis in chondrosarcoma patients." (PMID 33024108, 2020). "Finally, we investigated whether potential associations exist between gene amplification at the loci of HIF family genes, HIF1A or EPAS1, and various aspects of chondrosarcoma malignancy, including patient prognosis." (PMID 33024108, 2020).